GID4 (GID complex subunit 4 homolog)
Description:
Substrate-recognition subunit of the CTLH E3 ubiquitin-protein ligase complex that selectively accepts ubiquitin from UBE2H and mediates ubiquitination and subsequent proteasomal degradation of the transcription factor HBP1 (Probable). Binds proteins and peptides with a Pro/N-degron consisting of an unmodified N-terminal Pro followed by a small residue, and has the highest affinity for the peptide Pro-Gly-Leu-Trp. Binds peptides with an N-terminal sequence of the type Pro-[Ala,Gly]- [Leu,Met,Gln,Ser,Tyr]-[Glu,Gly,His,Ser,Val,Trp,Tyr]. Does not bind peptides with an acetylated N-terminal Pro residue.
Synonyms: C17orf39; VID24; VID2
Tractability: Small molecule: a structure with a bound ligand is known. PROTAC: ubiquitination databases record sites on it.
Chemical probes: PFI-7 (high quality)
Gene: Protein-coding gene on chromosome 17 (18,039,408 to 18,068,405, forward strand). Ensembl gene ENSG00000141034.
Subcellular location (Human Protein Atlas): Cytosol
Pathways (Reactome):
Metabolism: Regulation of pyruvate metabolism
Gene Ontology:
Biological process: proteasome-mediated ubiquitin-dependent protein catabolic process
Cellular component: ubiquitin ligase complex; cytosol; GID complex
Genetic constraint (gnomAD): Loss-of-function variants: 3 observed, 11.04 expected, observed/expected ratio (o/e) 0.27, 90% interval 0.12 to 0.7. The synonymous counts are far from expectation, so gnomAD's model fits this gene poorly and the ratio says little. Missense variants: 235 observed, 196.29 expected, observed/expected ratio (o/e) 1.2, 90% interval 1.08 to 1.33. Synonymous variants: 134 observed, 95.24 expected, observed/expected ratio (o/e) 1.41, 90% interval 1.22 to 1.62.
Homologues: Orthologues: macaque GID4 (99% identical), dog GID4 (88% identical), chimpanzee GID4 (73% identical), guinea pig GID4 (72% identical), mouse Gid4 (72% identical), pig GID4 (72% identical), rat Gid4 (72% identical), tropical clawed frog gid4 (66% identical), zebrafish GID4 (64% identical), rabbit GID4 (55% identical).
Diseases named in the same sentence as GID4 in open-access papers:
GID4 is named in the same sentence as 15 diseases in open-access papers, as found by Europe PMC text mining. Sharing a sentence is not in itself a finding about the gene and the disease. The quoted sentences say what the papers report.
osteosarcoma (4 papers, 2012 to 2022). A usually aggressive malignant bone-forming mesenchymal neoplasm, predominantly affecting adolescents and young adults. "In particular, CNV was more frequent in CCND3, AURKB, CCNE1, GID4, and MYC in P-AYA, while MDM2, CDKN2A/B, and FRS2 were more frequently altered in adult osteosarcoma (p < 0.001)." (PMID 35705558, 2022). "Of note, overexpression of genes belonging to the amplified region (COPS3, PMP22, GID4, ARGHAP44, TOP3A, SHMT1, and RASD1) was studied in osteosarcoma cell lines." (PMID 35920001, 2022).
angiosarcoma (2 papers, 2022 to 2023). A malignant tumor arising from the endothelial cells of the blood vessels. "Overall, the alteration prevalence for these genes was low, where GID4 was altered in 3.6% (83/2332) of soft tissue sarcoma nos, POT1 in 6.3% (38/606) of angiosarcoma, and RAD51B in 3.6% (38/1055) of uterus leiomyosarcoma samples." (PMID 37709802, 2023).
clear cell renal carcinoma (1 paper, 2024). A malignant epithelial neoplasm of the kidney characterized by the presence of lipid-containing clear cells within a vascular network. "Although the regulatory mechanisms controlling GID4-mediated ARHGAP11A degradation under physiological conditions remain to be examined, we note that ARHGAP11A expression is increased in various cancers, including hepatocellular and clear cell renal carcinoma and gastric cancer." (PMID 39389782, 2024).
metastatic disease (1 paper, 2023). "Next, we checked whether the presence of GID4 alterations impacted overall survival in sarcoma patients with metastatic disease." (PMID 37709802, 2023).
sarcoma (1 paper, 2023). A usually aggressive malignant neoplasm of the soft tissue or bone. "Our results propose a role played by RAD51B and GID4 in telomere elongation in sarcomas and open research opportunities for agents aimed at targeting this critical pathway in tumorigenesis." (PMID 37709802, 2023). "Across all sarcoma samples within our screening cohort, samples with alterations in either GID4, RAD51B, POT1, or ATRX had significantly higher telomeric content than WT samples." (PMID 37709802, 2023). "Prevalence of RAD51B, GID4, and POT1 alterations varied widely across sarcoma subtypes and tended to mostly occur in diseases with high prevalence rates of alterations in the other telomere maintenance genes." (PMID 37709802, 2023).
soft tissue sarcoma (1 paper, 2023). A malignant neoplasm arising from muscle tissue, adipose tissue, blood vessels, fibrous tissue, or other supportive tissues excluding the bones. "We observed that the median level of TERRA expression was significantly higher in GID4 altered soft tissue sarcoma nos vs WT (22.7 vs 9.1, p < 0.001)." (PMID 37709802, 2023). "Within soft tissue sarcoma nos, all the GID4 alterations were copy number amplifications with a median copy number of 7 (range 5–45 copies)." (PMID 37709802, 2023). "However the presence of a GID4 alteration on top of an ATRX alteration led to even higher telomeric content, within both soft tissue sarcoma nos and uterus leiomyosarcoma samples." (PMID 37709802, 2023). "In soft tissue sarcoma nos, median telomeric content of the double-altered samples was higher than either single GID4 altered or single ATRX altered samples, although neither reached statistical significance (1072 vs 1053 vs 874 TRPM, respectively, p > 0.05 for all comparisons)." (PMID 37709802, 2023).
cancer (3 papers, 2021 to 2024). A tumor composed of atypical neoplastic, often pleomorphic cells that invade other tissues. "It is thus tempting to speculate that loss of GID4 stabilizes ARHGAP11A in these cancer cells, thereby contributing to tumor progression." (PMID 39389782, 2024). "Some of these reported targets are cancer-related and are associated with carcinogenesis (such as SPRY2, SKY and SRSF3), cancer prognosis (such as CNOT6, RECK and GID4) or cancer cell plasticity (such as RMND5A)." (PMID 33804639, 2021). "GEPIA2 database analysis of 33 cancer types showed the following top 10 ALKBH5-related genes: GID4 (R=0.71), TOP3A (R=0.67), MAPK7 (R=0.66), NT5M (R=0.61), FLII (R=0.59), ZNF18 (R=0.57), DRG2 (R=0.57), COPS3 (R=0.56), MED9 (R=0.56) and PRPSAP2 (R=0.56) (all P<0.0001)." (PMID 35444654, 2022). "TIMER2 database was then used to confirm the association between ALKBH5 and the top 9 ALKBH5-related genes (GID4 was not annotated in TIMER2 portal) in 40 cancer types." (PMID 35444654, 2022).
tumor (2 papers, 2023 to 2024). "The impact of alterations in RAD51B, GID4, and POT1 on telomeric content was proportional to tumor purity, but in samples WT for known TMM genes, telomeric content was not impacted by tumor purity." (PMID 37709802, 2023).
GID4 also shares sentences with these, for which no sentence is quoted: acute pancreatitis (1 paper); bone tumors (1); gastric cancer (1); leiomyosarcoma (1); Multiple Organ Failure (1); uterus (1); uterus leiomyosarcoma (1).